ENSG00000273767
Gene: Miscellaneous RNA gene on chromosome 10 (121,949,412 to 121,949,487, reverse strand). Ensembl gene ENSG00000273767.
Homologues: Orthologues: mouse Gm56225 (87% identical).